PDX1 (pancreatic and duodenal homeobox 1)
Diseases named in the same sentence as PDX1 in open-access papers (continued):
Sharing a sentence is not in itself a finding about the gene and the disease.
tumor (continued). "Much like the KP model in the lung, a mouse strain expressing the mutated Kras G12D in pancreatic ductal cells (LSL-KrasG12D/+;Pdx-1-Cre; KC mice) was developed, resulting in a low tumor load after 5 months." (PMID 38111571, 2023). "We evaluated the efficacy of L_GEM and ONC201 in PanCan cells, and “KrasLSL-G12D; p53LoxP; Pdx1-CreER (KPC) triple mutant xenograft tumor-bearing mice." (PMID 37503215, 2023). "Compared to PDX2, the exosome concentration and YAP m5C level were much higher in PDX1, and the transplanted tumor size in PDX1 was significantly larger." (PMID 36123390, 2023). "Compared with that in normal mouse pancreas tissues, IHC also demonstrated elevated expression of USP8 in KPC (KrasLSL-G12D; Trp53LSL-R172H; Pdx1-Cre) tumor tissues, which had been initially activated in PanIN1 lesions." (PMID 36539510, 2023). "Pancreatic and duodenal homeobox 1 (PDX1) shifts from a tumor-suppressive to an oncogenic function after tumor transformation." (PMID 36400857, 2022). "In contrast, the B subtype of PanNETs that is high in PDX1, resembles to pancreatic β cells with a A-D-M WT tumor profile, but with more variable levels of PDX1 expression." (PMID 36139607, 2022). "Pancreas-specific deletion of Cxcr2 in KC mice prevents oncogene-induced senescence, increases tumor proliferation, and decreases survival (Pdx1-Cre; lox-stop-lox-KrasG12D/+; Cxcr2lox/lox)." (PMID 35159011, 2022). "PDX1 tumor-bearing mice treated with Ixa + Dina combination developed significantly smaller tumors and had the lowest growth rate as compared to vehicle- and single-drug-treated mice (P < 0.001)." (PMID 35971164, 2022). "To further investigate the role of HDAC5 in a model mimicking the mutational burden in human PDAC, we generated a mouse PDAC model using genetically engineered KPC mouse (KrasG12D/+; LSLTrp53R172H/+; Pdx-1-Cre) derived tumor cells." (PMID 35265200, 2022). "Separately, the Retinoblastoma (RB) protein, which is a well-known tumor and cell cycle suppressor, interacts with a specific structural motif within PDX1-HD." (PMID 36272648, 2022). "Positive expression of CR, CK5/6, WT1, and D2-40 were denoted in primary epithelioid tumor tissue, and PDX1 expressed the same pattern." (PMID 34789172, 2021). "It is known that upon neoplastic transformation, the role of PDX1 changes from tumor-suppressive to oncogenic." (PMID 34503200, 2021).
tumor (continued). "Although PDX1 expression is often increased during ADM and tumor onset, its downregulation or loss is mainly observed in poorly-differentiated tumors correlated with EMT and metastasis." (PMID 34888306, 2021). "Tissue morphology, presence of luminal markers PSA, NKX3.1, AR, CK8 expression, and absence of CK5+ basal cells indicated stable luminal epithelial morphology among the primary TUR-P tumor (T1), the PNmet, and PDX1–6 passages." (PMID 33602919, 2021). "While the primary tumor, the soft tissue metastasis, and the PDX-derived organoids showed a moderate, epithelial-specific staining for PD-L1, PDX1, and PDX2 tissues revealed a loss of expression of this marker in the epithelial compartment." (PMID 33602919, 2021). "The difference in Pdx1 and Cre mRNA expression at nine months of age was likely related to evaluation of KC female anus / tumor (tumor tissue harboring more Pdx1-Cre expressing cells) versus non-tumor anal tissue of males." (PMID 34735515, 2021). "During tumor formation, Pdx1 is upregulated in ADM and PanINs upon overexpression of TGFα or expression of oncogenic Kras." (PMID 34888306, 2021). "We scored nuclear positivity for ARX in 34 samples (52%), for PDX1 in 21 samples (32%), 3 tumours (5%) showed strong double positivity and 13 (20%) were negative for both TFs." (PMID 33288854, 2020). "Our identification of BLK as a differentially active tyrosine kinase in PDAC cells compared to wild-type pancreatic cells presents new insight into the role that the pancreatic and duodenal homeobox 1 (PDX1) transcription factor plays in tumor progression." (PMID 33213062, 2020). "In one case (patient 11), both observers noted heterogeneous (patchy) positive PDX1 expression in the primary tumor, which was also independently noted when scoring the corresponding cytologic specimen." (PMID 31846235, 2020). "At this time, the Pdx1 gene is expressed in pre-pancreatic endoderm, thus allowing Cre expression (hence tumor initiation) in virtually all pancreatic cell types." (PMID 33127675, 2020). "While only a subset of ARX+ tumours secreted glucagon (n = 7, 20% of all the ARX+ tumours), almost all the PDX1+ tumours produced insulin (n = 18, 95% of all PDX1+ tumours)." (PMID 33288854, 2020). "The overexpression of gene PDX1 can suppress the proliferation of tumor cells and induce the apoptosis of cancer cells." (PMID 31126066, 2019). "It has been reported that miR-141 is downregulated in a genetically engineered KrasG12D; Pdx1-Cre mouse (KC) model during tumor progression." (PMID 31852504, 2019). "This indicated that Pdx1 induction is present exclusively in the epithelial lesions of our adult KPF tumor model." (PMID 28934293, 2017). "Some of the most commonly used mouse models of PDAC, such as KPC (KRasLSL-G12D/WT; P53F/F; Pdx1-Cre), initiate oncogene expression at an embryonic stage, and the tumor cell of origin is unclear." (PMID 29069604, 2017). "Our results show that anti-PRR labelled with 125I (125I-anti-PRR) was significantly accumulated in tumor site of xenografts mice and Pdx1-cre; LSL-KrasG12D mice." (PMID 28874965, 2016). "As above, KPC mice (Pdx1-Cre; KrasLSL-G12D; p53lox/+) were generated on either Ptf1a+/+ or Ptf1aΔ/+ backgrounds, and animals were monitored for tumor-free survival." (PMID 26151762, 2015).
tumor (continued). "Analyses on 27 primary tumours confirmed the expression of some pluripotency genes (for example, OCT4 and KLF4) and endodermal stem cell traits (for example, SOX17 and PDX1) paralleling what was observed with the transplantable tumour line." (PMID 26437858, 2015). "Silencing PDX-1 efficiently inhibits tumor cell proliferation in vitro and tumor growth in vivo, showing that PDX-1 is a promising therapeutic target in cancer treatment." (PMID 25009500, 2014). "PDX-1 overexpression in benign and malignant cells resulted in increased tumor formation when these cells are implanted in mice." (PMID 22905092, 2012). "It should be noted that the PDX-1-Cre;Notch1lox/lox mice have Notch1 deleted from all pancreatic epithelial cells; however, other cells located in the tumor microenvironment, such as endothelial cells and immune cells, retain Notch1 expression." (PMID 23284900, 2012). "In the well-established KC (K-rasLSL.G12D/+; Pdx-1-Cre) mouse model of pancreatic cancer, a pancreas-specific deletion of ST6Gal1 delayed tumor formation and accompanying fibrosis, indicating a strong tumor-promoting role for this enzyme and for N-linked α2–6 sialic acids." (PMID 40885395, 2025). "Importantly, targeting PPY enhanced the efficacy of anti‐PD‐1 immunotherapy in KPC (KrasLSL‐G12D/+; Trp53LSL‐R172H/+; Pdx1‐Cre) mice, as evidenced by reduced tumor volume on 18F‐FDG PET‐CT imaging and prolonged overall survival." (PMID 40162859, 2025). "Importantly, targeting PPY enhanced the efficacy of anti‐PD‐1 immunotherapy in KPC (KrasLSL‐G12D/+; Trp53LSL‐R172H/+; Pdx1‐Cre) mice, as evidenced by reduced tumor burden on PET‐CT imaging and improved survival." (PMID 40162859, 2025). "To assess whether tumor and stromal phenotypes emerged in parallel and progress gradually, we first analyzed preneoplastic lesions from KrasG12D/+; Pdx1-Cre (KC) mice, in which PDAC precursor lesions arise through oncogenic Kras activation." (PMID 41006303, 2025). "Furthermore, ablation of the gut microbiome in KrasG12D/+; PTENflox/+; Pdx1-Cre mice resulted in decreased tumor growth and a reduction in the suppressive immune microenvironment." (PMID 40427173, 2025). "The evaluation of the anti-tumor effects of SIRPα-VEGFR1, a bispecific fusion protein that concurrently inhibits CD47 and VEGF, demonstrated significant tumor regression in the Hu-PDX1 model, comparable to the observed effects in the SIRPα-Fc + VEGFR1-Fc combination group." (PMID 38532108, 2024). "The tumor’s aggressiveness can be determined based on IPF1/PDX1 expression changes." (PMID 39239563, 2024). "Interestingly, in rare instances in which the pancreatic tissue section included both the PDAC tumor and the adjacent islets, high sorcin levels in PDAC tumors coincided with low insulin levels and PDX1 levels in tumor-adjacent islets." (PMID 39516378, 2024). "PDX1 staining was detected in both non-tumour and tumour tissue." (PMID 33906633, 2021). "PDX1 first acts as a tumor suppressor, maintaining the identity of acinar cells." (PMID 34503200, 2021).
tumor (continued). "Additionally, while PDX1 expression appears to be specific for benign and low stage tumours, ARX expression is retained at early and at advanced stages and only DAXX/ATRX status provides more information about stage and risk of disease progression." (PMID 33288854, 2020). "We examined tumor development in the gallbladder of KrasLSL-G12D/+;Pdx1-Cre (KC) mice." (PMID 29142904, 2017). "E-cadherin mRNA levels were reduced in Pdx1-Cre;KrasG12D/+;SnailKI/+;Cdh1lox/+ animals, which showed dramatically shortened median survival (78 days) compared to Pdx1-Cre; KrasG12D/+;SnailKI/+ (166 days) mice and a clear shift of the tumours towards an undifferentiated mesenchymal phenotype." (PMID 36882420, 2023). "In vitro, PDX1 tumor cells could be markedly suppressed by anlotinib." (PMID 35992875, 2022). "Moreover, most samples with strong hypo-methylation of PDX1 in subgroup T1 were functional tumours." (PMID 33536587, 2021). "We speculate that cutaneous aggravation or micro-wounds due to grooming and scratching may trigger an inflammatory reaction and wound healing processes with upregulated Pdx1 and Notch expression, thus forming a tumor-prone environment in Pdx1-Cre;Kras;N1ko mice." (PMID 21042537, 2010). "Further validation also revealed the presence of transcripts transferred via extracellular vesicles (including the Pdx1-CreERT2 transgene from the KPC mouse model), suggesting a novel mechanism of tumor-neuron interaction." (PMID 41847880, 2026).
tumor (continued). "Crossing conditional knockout of Lfng into KrasG12D;Pdx1-Cre mice resulted in accelerated PDAC development, suggesting a tumor-suppressive role for Lfng in this context." (PMID 39548190, 2025). "We implanted DLL4 overexpression and knockdown PDX cell lines subcutaneously into T/B-deficient nude mice to investigate whether DLL4 affects TNBC development in TTN-deficient mice, and tumor burden was limited by DLL4 expression in PDX1/PDX2 regardless of TTN genotype." (PMID 41326912, 2025). "The anti-human Gal-9 ab (1G3) was tested in a K-rasLSL.G12D/+;Pdx-1-Cre (KC) mouse of PDA where it reduced Treg, and increased CD4+ T cell, tumor infiltration and suppressed PDA progression." (PMID 40869319, 2025). "All neoplasms were investigated with immunohistochemistry for neuroendocrine markers (Synaptophysin, Chromogranin-A), ATRX, DAXX, ARX, and PDX1 transcription factors." (PMID 39331358, 2024). "Using immunohistochemical (IHC) score and gene expression analysis of patient tumor tissues, we determined that PDX2 expressed high levels of circHAS2, whereas PDX1 expressed lower levels." (PMID 38515149, 2024). "Conversely, other literature indicates that silencing GLUL expression inhibits nucleotide synthesis, suppresses tumor growth in LSL-KrasG12D/+; Pdx1-Cre (KPC) PDAC mice, and increases survival rates." (PMID 39519347, 2024). "Both Lepob/ob and Leprdb/db accelerated oncogenic Kras-driven tumor progression in Pdx1-Cre;KrasLoxP-STOP-LoxP-G12D (KC) mice and enhanced tumor growth and metastasis in syngeneic transplant models." (PMID 37648285, 2023). "The differences in levels of seven EMT-associated markers, Ki-67, DAXX, CD24, CD44, vimentin, laminin and PDX1 plus CgA and NSE (neuroendocrine markers) enabled a distinct molecular signature for each tumour grade to be generated." (PMID 36362433, 2022). "Markers CD24, CD44, PDX1, synaptophysin, CD49, CDX2, CD45, DAXX, PCAD and CK7 had lower expression in the tumour relative to that in the non-tumour with the exception of one patient." (PMID 36362433, 2022).